RAC3 (Rac family small GTPase 3)
Description:
Plasma membrane-associated small GTPase which cycles between an active GTP-bound and inactive GDP-bound state. In active state binds to a variety of effector proteins to regulate cellular responses, such as cell spreading and the formation of actin-based protusions including lamellipodia and membrane ruffles. Promotes cell adhesion and spreading on fibrinogen in a CIB1 and alpha-IIb/beta3 integrin-mediated manner.
Tractability: Small molecule: a structure with a bound ligand is known. Antibody: its Gene Ontology location is reachable by antibodies, with high confidence; UniProt places it where antibodies can reach, with medium confidence. PROTAC: UniProt records ubiquitination sites on it; ubiquitination databases record sites on it; its protein half-life has been measured; a small molecule that binds it is known.
Target class: Enzyme; Hydrolase
Gene: Protein-coding gene on chromosome 17 (82,031,637 to 82,034,204, forward strand). Ensembl gene ENSG00000169750.
Subcellular location: Cytoplasm; Endomembrane system; Cell projection, lamellipodium; Cytoplasm, perinuclear region; Cell membrane; Cytoplasm, cytoskeleton
Pathways (Reactome):
Signal Transduction: PCP/CE pathway; RAC3 GTPase cycle
Gene Ontology:
Molecular function: calcium-dependent protein binding; GTPase activity; protein binding; G protein activity; GTP binding
Biological process: actin cytoskeleton organization; cell projection assembly; positive regulation of cell adhesion mediated by integrin; positive regulation of substrate adhesion-dependent cell spreading; postsynaptic actin cytoskeleton organization; Wnt signaling pathway; actin filament organization; cell chemotaxis; establishment or maintenance of cell polarity; intracellular signal transduction; motor neuron axon guidance; Rac protein signal transduction; regulation of cell shape; regulation of neutrophil migration; respiratory burst; regulation of cell-substrate adhesion; regulation of postsynapse assembly; small GTPase-mediated signal transduction
Cellular component: cell periphery; cytoplasm; endomembrane system; extracellular exosome; filamentous actin; glutamatergic synapse; growth cone; neuron projection; neuronal cell body; perinuclear region of cytoplasm; cytoplasmic vesicle; cytoskeleton; cytosol; endoplasmic reticulum membrane; NADPH oxidase complex; plasma membrane; lamellipodium; postsynapse
Genetic constraint (gnomAD): Loss-of-function variants: 9 observed, 21.64 expected, observed/expected ratio (o/e) 0.42, 90% interval 0.25 to 0.73. The upper end of that interval is the gene's LOEUF score, 0.73, which puts it in group 2 of 6, group 1 being the genes least tolerant of losing a copy. Missense variants: 195 observed, 261.8 expected, observed/expected ratio (o/e) 0.74, 90% interval 0.66 to 0.84. Synonymous variants: 141 observed, 112.7 expected, observed/expected ratio (o/e) 1.25, 90% interval 1.09 to 1.44.
Homologues: Orthologues: dog RAC3 (100% identical), guinea pig RAC3 (100% identical), macaque RAC3 (100% identical), mouse Rac3 (100% identical), pig RAC3 (100% identical), rat Rac3 (100% identical), chimpanzee RAC3 (99% identical), zebrafish rac3a (98% identical), zebrafish rac3b (96% identical), tropical clawed frog rac3 (92% identical), Caenorhabditis elegans rac-2 (76% identical). Paralogues in human: RAC1 (93% identical), RAC2 (89% identical), CDC42 (70% identical), RHOG (70% identical), RHOQ (65% identical), RHOJ (61% identical), RHOU (57% identical), RHOA (54% identical), RHOB (54% identical), RHOC (53% identical), RHOV (53% identical), RHOD (50% identical), and 10 more.
Diseases named in the same sentence as RAC3 in open-access papers:
RAC3 is named in the same sentence as 65 diseases in open-access papers, as found by Europe PMC text mining. Sharing a sentence is not in itself a finding about the gene and the disease. The quoted sentences say what the papers report.
breast cancer (30 papers, 2005 to 2025). A primary or metastatic malignant neoplasm involving the breast. "RAC3 inhibition also caused a significant reduction of both invasion and adhesion of breast cancer cells through the ERK-2/NF-κB signaling pathway." (PMID 37056933, 2023). "The activation of Rac3 is associated with an invasive and metastatic phenotype of breast cancer cells." (PMID 34257551, 2021). "The Rac effector p21-activated kinase (Pak) is associated with active Rac3, the Rac3-Pak pathway is critical for DNA synthesis, and hyperactive Rac3 controls the proliferation of breast cancer cells by a p21-activated kinase-dependent pathway." (PMID 34257551, 2021). "For example Rac3 GTPase, which is linked to breast cancer, cellular migration and adhesion, is transcriptionally upregulated by DEAF1 in immortalised mammary epithelial cells." (PMID 22723967, 2012). "Because Rac1 and Rac3 both have been implicated in breast cancer, we carried out a comparative study between the two isoforms." (PMID 16280046, 2005). "In addition, SOCS3 has previously been reported to be hypermethylated in melanoma, while loss of RAC3 expression has been associated with impaired invasion in glioma and breast carcinoma cells." (PMID 36125262, 2022). "In a previous work performed in primary cutaneous melanoma samples, the authors described RAC3 as a prognostic marker for the prediction of survival associated with melanoma, while in breast cancer the RAC3 overexpression was considered as a predictor of resistance to Tamoxifen treatment." (PMID 29209153, 2017). "Several studies have indicated that RAC3 plays a pivotal role in facilitating the invasion and metastasis across a spectrum of malignancies, encompassing bladder cancer, breast cancer, and lung adenocarcinoma." (PMID 40123831, 2025). "Among them, MVD, a member of the mevalonate pathway, interacts with RAC3 in HER2-positive breast cancer." (PMID 40564925, 2025). "In typical circumstances, RAC3 is mainly found in brain tissue and neuronal cells, yet its expression is upregulated in breast cancer, prostate cancer, and brain tumors." (PMID 39872053, 2024). "In aggressive breast cancer, RAC3’s specific binding partner CIB1 facilitates the recruitment of RAC3, promoting integrin activation at invasive pseudopodia, thereby regulating adhesion and degradation of the extracellular matrix (ECM)." (PMID 39872053, 2024). "RAC3 expression is frequently elevated in a diverse range of human cancers, including colon carcinoma, lung adenocarcinoma, breast cancer, pancreatic cancer, and bladder cancer, which has been verified to be a crucial regulator in tumor initiation." (PMID 38987564, 2024). "RAC3 regulates breast cancer invasion and metastasis by controlling adhesion and matrix degradation, and promotes proliferation, migration, and invasion in bladder cancer via PYCR1/JAK/STAT signaling." (PMID 38200409, 2024). "The RAC3 gene was amplified in breast cancer and correlated with tumor size and estrogen as well as progesterone receptor positivity." (PMID 36936912, 2023). "RAC3 is considered to function as an oncogene and was originally found to be highly expressed in breast cancer." (PMID 33782686, 2021). "siRNA-mediated depletion of Rac3 strongly inhibits the invasive behaviors of glioblastoma and breast carcinoma cells." (PMID 34257551, 2021). "Consistent with this cell line data, hyperactive Rac3 was also found in human metastatic breast cancer tissues." (PMID 32992837, 2020). "RAC3 has been proven to participate in cell migration, adhesion and apoptosis, playing an important role in breast cancer and lung adenocarcinoma." (PMID 33184436, 2020). "This group first isolated cDNAs for Rac1, Rac2 and Rac3 genes from various breast cancer cell lines and performed Sanger sequencing on them." (PMID 32992837, 2020). "In support of Rac1 function in breast cancer, studies have also shown that Rac3 activation promotes invasion." (PMID 32992837, 2020).
breast cancer (continued). "The same study has shown that in breast cancer cells, the activity of Rac3 is critical for integrating the integrin-mediated invadopodia adhesion to the ECM, with the delivery of metalloproteases at invadopodia to degrade the ECM." (PMID 31514269, 2019). "In non-invasive MCF-7 breast cancer cells, although Rac3 is expressed at similar levels to MDA-MB-231 cells, it does not support aggressiveness because the low expression of NF-κB subunits renders this pathway non-functional in these cells." (PMID 31514269, 2019). "Rac3 is expressed in different types of human tumors including breast cancer, glioblastoma, prostate cancer, and lung adenocarcinoma." (PMID 31514269, 2019). "The human gene for Rac3 maps to chromosome band 17q25.3, near a region that is frequently deleted in breast cancer." (PMID 31514269, 2019). "Knockdown of Rac3, but not of Rac1 or Rac2, induces autophagy in different tumor cell lines, including prostate cancer PC3 and breast cancer MDA-MB-231 cells that express low levels of Rac3." (PMID 31514269, 2019). "Rac3 depletion in invasive MDA-MB-231 breast cancer cells strongly reduces invasion and increases Tumor Necrosis Factor (TNF)-induced apoptosis, supporting a role for Rac3 in the aggressiveness of these tumor cells." (PMID 31514269, 2019). "Rac3 is an important driver of invasion and formation of metastasis in vivo, as shown by the strong reduction of lung metastases in a mouse model injected with Rac3 knockout breast cancer cells compared to control cells expressing normal Rac3 levels." (PMID 31514269, 2019). "The first evidence of the critical and distinct implication of Rac3 on the invasive behavior of breast carcinoma cells and glioblastoma cells has been obtained by silencing the expression of either Rac3 or Rac1 by RNA interference." (PMID 31514269, 2019). "RAC3 is highly expressed in several human cancers such as breast cancer, prostate cancer and liver cancer and has been demonstrated to be a key regulator in tumor initiation, progression, metastasis and survival." (PMID 29209153, 2017). "The gene for this molecule was reported to be amplified in 2–10% of human breast tumors and the protein overexpressed in 30–60% of tumors, suggesting that RAC3 provides a growth advantage for breast cancer cells." (PMID 29209153, 2017). "Aberrant activation of Rac3 has been recognized to be important in tumor proliferation in both breast cancer and prostate cancer." (PMID 24684802, 2014). "Rac3, as an oncogene protein, plays a pivotal role in tumorgenesis of a variety type of cancers, including breast cancer and prostate cancer." (PMID 24684802, 2014). "Rac3 was found to be involved in breast cancer cell aggressiveness through the activation of NF-κB and Erk2." (PMID 24684802, 2014). "Our results thus confirm the crucial role of Rac3 in breast cancer aggressiveness and show the potential usefulness of Rac3 depletion in breast cancer therapy." (PMID 23388133, 2013). "Transfection of breast cancer cell lines with siRNA anti-Rac3 significantly decreased the proliferation of MDA-MB-231 but not MCF-7 cells after 72 h and 96 h of treatment." (PMID 23388133, 2013). "Our aim in this study was to examine the effects of Rac3 in breast cancer cell aggressivity in both the invasive MDA-MB-231, which have a spontaneous activation of RhoA, and in the non-invasive MCF-7, which do not." (PMID 23388133, 2013). "Rac3 appeared to be of most interest since its expression has previously been reported in breast cancer epithelial cells." (PMID 18826651, 2008). "Depletion of Rac3 from BT549 breast carcinoma cells by RNAi strongly inhibited cell invasion revealing a role for this GTPase in breast cancer metastasis." (PMID 18826651, 2008). "In this study, we also demonstrate the efficacy of both the Rac1 and Rac3 isoforms in the malignant progression of human breast cancer." (PMID 16280046, 2005).
breast cancer (continued). "The research presented here establishes a direct role for Rac3 in cell functions relevant for breast cancer progression." (PMID 16280046, 2005). "Taken together, these data establish the efficacy of both Rac1 and Rac3 in human breast cancer progression." (PMID 16280046, 2005). "More experiments are needed, however, to show that Rac1 actually acts differently to Rac3 with respect to human breast cancer." (PMID 16280046, 2005). "Taken together, these data suggest a direct role for both Rac1 and Rac3 protein activation in the metastatic progression of human breast cancer." (PMID 16280046, 2005). "Taken together, these data substantiate not only a vital role for Rac1 in cell functions relevant for breast cancer metastasis, but also a vital role for Rac3." (PMID 16280046, 2005). "To investigate the migratory and invasive potential of the Rac isoforms in human breast cancer, namely Rac1 and the subsequently cloned Rac3, we stably expressed either dominant active Rac1 or dominant active Rac3 into the least metastatic cell variant." (PMID 16280046, 2005). "To establish a role for both Rac1 and Rac3 in human breast cancer, we carried out a comparative study of the invasive capabilities between the two isoforms." (PMID 16280046, 2005). "We found that Rac3 activation alone can significantly increase in vitro metastatic properties in human breast cancer cells." (PMID 16280046, 2005). "Taken together, these results suggest a role for both the Rac1 and Rac3 GTPases in human breast cancer progression." (PMID 16280046, 2005). "Rac3 is another critical protein required to regulate adhesiveness and motility in breast cancer." (PMID 38786043, 2024). "Moreover, endogenous, hyperactive RAC3 controls breast cancer cell proliferation through a p21-activated kinase-dependent pathway." (PMID 38200409, 2024). "For example, RAC3 promotes the growth of breast cancer cells through the p21-activated kinase-dependent pathway, enhances the proliferation of cancer cells in vitro and in vivo, and facilitates proliferation, migration, and invasion of bladder cancer cells through the PYCR1/JAK/STAT axis." (PMID 38987564, 2024). "Furthermore, RAC3 inhibited apoptosis and promoted tumour invasion, high expression of which indicated a poor prognosis for breast cancer." (PMID 37386813, 2023). "RAC3 was also demonstrated to promote invasion and metastasis in breast cancer and bladder cancer." (PMID 35814377, 2022). "Few studies have assessed the role of Rac3 in breast cancer." (PMID 36555156, 2022). "Interestingly, we found reduced RAC3 gene expression in the tumors of our HR-positive/HER2-positive breast cancer patients who achieved pCR, interacting with the MVD gene of the mevalonate pathway." (PMID 36555156, 2022). "One of the mechanisms that may lead to the overexpression of Rac3 in breast cancer has been recently described." (PMID 31514269, 2019). "In breast cancer RAC3 regulates invasion and migration participating in the metastatic process." (PMID 30990809, 2019). "In contrast, overexpression of Rac3 promotes estrogen-induced breast cancer cell migration." (PMID 24684802, 2014). "Firstly, we sought to clarify the role of Rac3 in breast cancer cell aggressiveness." (PMID 23388133, 2013). "In contrast, the role of Rac3 in the aggressiveness of breast cancer cells is not well established: in some studies Rac3 was found to be involved mainly in cell proliferation, whereas in others Rac3 has been implicated in cell invasion but not migration." (PMID 23388133, 2013). "Moreover, Rac3 proteins are frequently overexpressed and mutated in human brain tumours, which may be associated with aggressive tumour behaviour; and transfection of a dominant active variant of Rac3 into low metastatic breast cancer cells leads to an increase of cell invasiveness." (PMID 23388133, 2013). "Firstly, we analyzed the effects of Rac3 depletion on the breast cancer cells’ aggressiveness." (PMID 23388133, 2013).
breast cancer (continued). "EHT 1864 is likely to be superior to using a Rac GEF inhibitor, which will not have any effect on the Rac1b or Rac3, long considered to be associated with breast cancer aggressiveness." (PMID 22689141, 2012). "Over-expression of Rac1 and Rac3 GTPases has been noted in several small cohorts of breast cancers and it has been suggested that they may have a role in resistance to endocrine treatment." (PMID 22689141, 2012). "Moreover, dominant activation of Rac3 in the mammary epithelium has been shown to lead to the formation of mammary lesions, although a direct role for Rac3 in breast cancer invasion and metastasis has yet to be substantiated." (PMID 16280046, 2005). "Currently, we are testing the hypothesis that Rac3 activation alone can increase breast cancer metastasis in vivo by using the nude mouse model of experimental metastasis." (PMID 16280046, 2005). "In addition, compared with the low RAC3 expression, the high RAC3 expression was linked to poorer outcomes in individuals with bladder cancer, KIRC, sarcoma, and thyroid carcinoma, but longer survival in breast cancer and PDAC." (PMID 40123831, 2025). "Rac3 may be a potent target for inhibiting aggressive breast cancer." (PMID 23388133, 2013). "Initially, overexpression of AIB1, RAC3, and TRAM1 (known as ACTR) was found to promote proliferation in breast cancer (BC) and to confer anti-E2 resistance." (PMID 41154392, 2025). "RAC3 in active GTP‐bound state acts as a co‐activator of the transcription factor ERα to induce cell proliferation and migration of breast cancer." (PMID 40123831, 2025). "RAC3 facilitates proliferation and invasion of bladder cancer cells via PYCR1/JAK/STAT signaling 26, and promotes invasion and metastasis of breast cancer cells through modulating adhesion and matrix degradation." (PMID 37056933, 2023). "This work was conducted to analyze the implication of Rac3 in the aggressiveness of two breast cancer cell lines, MDA-MB-231 and MCF-7: both express Rac3, but MDA-MB-231 expresses more activated RhoA." (PMID 23388133, 2013). "Recent data from breast cancer cell lines shows that miR-17-5p of the miR17-92 cluster down regulates the proto-oncogenic transcriptional activator AIB1 (amplified in breast cancer 1), also known as SRC-3, TRAM1, NCOA3 and RAC3." (PMID 21532838, 2010). "AIB-1 (also called SRC3, RAC3, ACTR and p/CIP), a co-activator of estrogen receptor commonly amplified in breast cancer cells, was used as a loading control." (PMID 16168116, 2005). "There have been few studies on the effects of Rac3 on the aggressiveness of breast cancer cells, and the results obtained do not always agree." (PMID 23388133, 2013). "All these effects of MET, MMP- 2 downregulation and migratory-invasive behavior inhibition, were also obtained in the human mammary cancer T47-D cells where its natural high RAC3 expression was stably inhibited by an shRAC3 RNA (data not shown), demonstrating that is not exclusive of colon cancer." (PMID 29464039, 2018). "To answer these questions, we examined the consequences of Rac3 inhibition by siRNA in two breast cancer cell lines: MDA-MB-231 (Estrogen Receptor (ER) negative), an aggressive line that overexpresses constitutively activated RhoA; and MCF-7 (ER positive), which is not invasive." (PMID 23388133, 2013). "However, Rac3-mediated invasion may be specific for TNBC as reduction of Rac3 in MCF-7 cells, a less aggressive and luminal breast cancer cell line, did not have any significant effects on parameters of aggressiveness." (PMID 32992837, 2020).